ENSG00000243696 (novel MUSTN1-ITIH4 readthrough)
Gene: Protein-coding gene on chromosome 3 (52,813,282 to 52,835,729, reverse strand). Ensembl gene ENSG00000243696.
Genetic constraint (gnomAD): Missense variants: 87 observed, 78.75 expected, observed/expected ratio (o/e) 1.1, 90% interval 0.93 to 1.32. Synonymous variants: 34 observed, 28.93 expected, observed/expected ratio (o/e) 1.18, 90% interval 0.89 to 1.56.